INS (insulin)
Diseases named in the same sentence as INS in open-access papers (continued):
Sharing a sentence is not in itself a finding about the gene and the disease.
Insulin resistance (continued). "Moreover, certain pathophysiological traits of GDM, such as insulin resistance and the limited capacity of β-cells to increase insulin secretion, may be latent before pregnancy, becoming apparent due to the metabolic demands of gestation." (PMID 39770967, 2024). "Our present study confirmed that supplementation of ω-3 PUFA improved insulin resistance and reversed the metabolic abnormalities observed in the soleus skeletal muscle in the obese model by activation of fatty acid oxidation modulators and the insulin signaling pathway." (PMID 38399437, 2024). "Excessive adiposity significantly and persistently affects insulin sensitivity in adipose tissue, skeletal muscle, and liver among children with obesity, and insulin resistance may arise in some of these tissues prior to the onset of T2DM in individuals with obesity." (PMID 40302954, 2024). "In this way, it is difficult to assume a general standardized suggestion regarding the initial insulin dose in IRD cases since the patient’s insulin-resistance degree (i.e., presence of interferences of insulin action on target cells) and residual beta-cell secretory capacity are unknown." (PMID 38539988, 2024). "In addition, insulin levels are associated with an increase in short-chain fatty acids(SCFAs), and its decrease may increase insulin levels and improve insulin resistance." (PMID 39114293, 2024). "Therefore, further studies are required to investigate the ‘selective insulin resistance hypothesis’ in the context of the pathway-specific effects of insulin signaling." (PMID 39195275, 2024). "Because, insulin resistance, a common concern in aging, (e.g., brain-specific insulin signaling deficiencies in the early stages of AD pathogenesis,) is linked to cognitive decline, BDNF interaction with insulin is crucial for maintaining energy metabolism and cognitive function." (PMID 39656488, 2024). "Insulin resistance in T1D could also be related to the insulin administration route." (PMID 39906033, 2024). "The precise impact of insulin and insulin resistance on amino acid metabolism remains unclear." (PMID 39683486, 2024). "Notably, the heightened MIF levels are closely linked to insulin resistance, with a primary reliance on increased blood insulin levels rather than glucose." (PMID 38802393, 2024). "Additionally, a comprehensive analysis of intervention studies indicated that vitamin D supplementation significantly reduced fasting blood sugar, hemoglobin A1c (HbA1c), insulin concentrations, and homeostatic model assessment for insulin resistance (HOMA-IR)." (PMID 38216955, 2024). "However, some clinical studies indicate that IF may not have satisfactory improvement effects on blood glucose levels, insulin sensitivity, or insulin resistance in obese individuals." (PMID 39238846, 2024). "While changes in INSR or downstream pathways are most often evoked to explain insulin resistance at the molecular level, it must also be kept in mind that the bioactivity of insulin itself may vary according to its quaternary structure or soluble component in the surrounding matrix." (PMID 37611907, 2024). "The beneficial effects of vitamin D on mortality in diabetic patients may be mediated by its ability to improve insulin sensitivity, exert anti-inflammatory effects, and provide cardiovascular protection, thereby attenuating the adverse impact of TyG (insulin resistance) on mortality." (PMID 39744244, 2024). "Third, other insulin signaling molecules or pathways we did not assess could be also important in the association between brain insulin resistance and cognitive decline and may warrant further investigation." (PMID 38029396, 2024). "Indeed, peripheral insulin level was the strongest determinant of insulin resistance in this study." (PMID 39906033, 2024).
Insulin resistance (continued). "Moreover, it has been shown that dietary fat acutely increases insulin resistance in human skeletal muscles and glucose concentrations and insulin requirements in patients with type 1 diabetes and that high-fat meals elicit negative effects on endothelial cells." (PMID 39766992, 2024). "We could not show the causal relationship between insulin resistance and altered insulin signaling in skeletal muscles in our model." (PMID 39430205, 2024). "On the other hand, given the high post-meal glycaemia and insulin values of the Mediterranean diet, the ketogenic diet is significantly better in controlling these parameters, which directly translates into a lower likelihood of occurrence of the main risk factor for MAFLD, i.e., insulin resistance." (PMID 39200999, 2024). "Furthermore, glutathione peroxidase 1 (GPX1), a selenium-containing antioxidant enzyme, has been discovered to inhibit insulin signaling by lowering reactive oxygen species levels, resulting in insulin resistance and possibly affecting pancreatic β-cell function." (PMID 39149550, 2024). "Post-binding steps in insulin signaling, such as reduced TK activity, a decreased expression of insulin receptor substrate-1 (IRS-1), and increased levels of the p85α subunit of PI 3-kinase, are mainly involved as causes of insulin resistance in women with gestational diabetes mellitus." (PMID 38539988, 2024). "DPH5 could promote glucose uptake and consumption of IR-HepG2 cells, accelerate glucose utilization, and improve insulin resistance and insulin sensitivity by regulating PI3K/AKT-GSK3β signaling pathway and increasing the expression of GLUT4 and GSK3β proteins." (PMID 38799166, 2024). "However, studies show that non-diabetic individuals have the ability to counteract the insulin resistance caused by glucocorticoids by either enhancing pancreatic β-cell activity or increasing insulin secretion and sensitivity." (PMID 38791468, 2024). "These compounds may regulate blood lipid levels through various mechanisms, such as enhancing fat hydrolysis, boosting HDL-C activity and levels, augmenting antioxidant capabilities, curtailing the creation of natural lipids, and regulating insulin levels to reduce insulin resistance." (PMID 39065719, 2024). "Additionally, I3C treatment could improve insulin sensitivity, glucose tolerance, and insulin resistance and also regulate lipid metabolism disorders in HFD-fed mice." (PMID 39830328, 2024). "Six proteins function in regulating glucose homeostasis, insulin resistance, and β-cell function, including SHBG, FETUB, PRG4, GSN, CFD, and TF, among which SHBG and FETUB are markers of insulin sensitivity and the expression of TF in adipose tissue is positively associated with insulin sensitivity." (PMID 38182717, 2024). "However, the development of insulin resistance in these mice could completely be reversed by administering a phosphatidylinositol 3-kinase inhibitor, suggesting that the blockade of insulin-mediated signaling may prevent insulin resistance (see further below)." (PMID 38791525, 2024). "We considered it important to test for an interaction between empagliflozin and insulin’s actions on vascular function, given empagliflozin’s strong impact on heart failure, CVD, and renal function outcomes and given the association of each of these pathologies with metabolic insulin resistance." (PMID 38170166, 2024). "Importantly, we also detected that circulating levels of endotoxin, LBP, zonulin and S100A8 were associated with insulin resistance, due to the positive correlation with insulin levels and HOMA index and the negative association with QUICKI index." (PMID 38315242, 2024). "Although our results show associations between the transition through stages of type 1 diabetes and measures of insulin resistance and insulin sensitivity, causality could not be determined." (PMID 37914981, 2024).
Insulin resistance (continued). "Indeed, salt absorption in the proximal tubule is enhanced in humans with insulin resistance due to the preservation of the stimulatory effect of insulin (compensatory hyperinsulinemia) on salt reabsorption in the kidney proximal tubule, resulting in a state of salt overload and HTN." (PMID 39085768, 2024). "Additionally, genetic mutations, for example in the peroxisome proliferator-activated receptor gamma (PPARγ) gene, may play a role in the development of insulin resistance by leading to altered insulin levels, molecular signaling and lipid metabolism." (PMID 38791018, 2024). "Furthermore, eTRC appeared to be as effective as conventional dieting for the management of multiple cardiometabolic risk factors, encompassing overweight, increased whole-body and visceral adiposity, insulin resistance, impaired insulin clearance and dyslipidaemia." (PMID 37971503, 2024). "What if one of the major causes of insulin resistance is not related to defects in the target tissues and/or insulin receptor signaling, but rather to a reduced survival of endogenously secreted insulin on its way to activating the receptor on the cell surface of the target tissues?" (PMID 40604313, 2024). "In addition, paracrine/autocrine signaling to nearby pre-adipocytes/adipocytes or immune cells could modulate insulin signaling in adipose tissue, indirectly affecting whole-body insulin resistance." (PMID 38967989, 2024). "Additionally, CHI3L1 may be associated with insulin resistance and obesity in the pathogenesis of NASH, and hepatic insulin sensitivity can be partially restored by parenteral given anti-Chi3L1 monotherapy." (PMID 38962736, 2024). "Furthermore, methylation levels of the PPARγ coactivator 1α promoter correlated with homeostasis models assessing insulin resistance and fasting insulin, whereas methylation levels of the mitochondrial transcription factor A promoter negatively correlated with fasting insulin." (PMID 39872862, 2024). "Furthermore, NOx-induced inflammation may impair insulin signaling pathways in adipose tissue, exacerbating insulin resistance and metabolic dysfunction." (PMID 39337093, 2024). "Alpha-aminoadipic acid is also hypothesized to modulate insulin secretion and glucose homeostasis by contributing to the initial compensatory upregulation of insulin secretion to maintain glucose homeostasis in early insulin resistance." (PMID 39394552, 2024). "Lachnospiraceae bacterium 3_1_57FAA_cT1 is a potentially beneficial microorganism that is inversely proportional to homeostatic model assessment of insulin resistance (HOMA-IR) and fasting insulin levels and may mediate the impact of obesity on insulin resistance." (PMID 38558794, 2024). "Furthermore, incubation with insulin increased the proliferation of immature SCs37, and, therefore, insulin resistance occurring in obese boys may disrupt this process, leading to a depletion of the SC pool." (PMID 38961093, 2024). "Furthermore, multiple miRNAs within ATMs-EVs might act in a coordinated manner to induce insulin resistance and insulin-sensitive phenotypes." (PMID 39735643, 2024). "Moreover, the Insulin Tolerance Test (ITT) showed that the insulin resistance of the HFD group was significantly higher than that of the ND group, and the insulin resistance of K. lactis, LP8198, and the combination of K. lactis and LP8198 groups was alleviated." (PMID 38611428, 2024). "Insulin resistance (IR) is strongly associated with obesity and often coexists with type 2 diabetes (T2D) and metabolic dysfunction-associated steatotic liver disease (MASLD) and is characterized by elevated circulating levels of insulin, glucose, and triglycerides." (PMID 39353069, 2024). "Insulin resistance diminishes the expression of insulin receptors in the brain, which in turn impairs neuronal plasticity, neuroprotection, neuronal growth, and energy metabolism—key functions that insulin normally supports under healthy physiological conditions." (PMID 39335505, 2024).
Insulin resistance (continued). "Thus, measuring glucose uptake by cultured myotubes is a reliable method to assess whether an intervention can improve insulin responsiveness or correct insulin resistance." (PMID 38474229, 2024). "However, some individuals with type 1 diabetes may develop insulin resistance due to obesity or long-term insulin therapy, a condition sometimes referred to as “double diabetes,” which may increase the risk of developing NAFLD." (PMID 39664063, 2024). "However, STING may play additional roles in β-cell GSIS, as STING knockout mice, although protected from insulin resistance exhibited diminished insulin responses." (PMID 38404962, 2024). "However, in T2D, targeted metabolic inhibition using nutritional and/or pharmacological compounds could prevent insulin resistance and improve insulin sensitivity in prediabetic and diabetic animal models and in diabetic patients." (PMID 38255314, 2024). "T1D is characterized by insulin deficiency due to depletion of pancreatic B-cells, while type 2 diabetes is characterized by elevated blood insulin in the early stages due to insulin resistance, and therefore it has been hypothesized that insulin promotes the metabolic synthesis of bone." (PMID 38751603, 2024). "Consequently, persistent preoperative hyperglycemia may contribute to the occurrence of POD through insulin resistance and declining insulin levels." (PMID 38977983, 2024). "However, most studies concur that the use of natural sweeteners (stevia, hoodia, and agavis syrup) may reduce insulin resistance, increase insulin sensitivity, and improve glycemic control in patients with type 1 and type 2 diabetes." (PMID 39339762, 2024). "Moreover, muscle being a crucial site for insulin-stimulated glucose absorption, the lower FFMI in the LBW children may increase their future risk of insulin resistance." (PMID 39268361, 2024). "Additionally, we assessed these concentrations in relation to biochemical markers of metabolic syndrome in the obese participants, including triglycerides, HDL cholesterol, fasting blood glucose and insulin levels, as well as the insulin resistance index (HOMA-IR)." (PMID 39597065, 2024). "Furthermore, the percentage of Th1 cells producing IFN-γ has been shown to exhibit a positive correlation with insulin resistance in obese patients, as evidenced by elevated levels of leptin, insulin, and homeostatic model assessment of insulin resistance (HOMA-IR) values." (PMID 39148730, 2024). "Furthermore, multiplex analysis of metabolism-related hormone levels in serum collected at sacrifice revealed increased insulin levels in the vehicle-treated group, suggestive of insulin resistance, while insulin levels were similar to baseline in ONX-0914 treated animals." (PMID 38660806, 2024). "However, the AF1 peptide did not completely normalize ERα deficiency-induced insulin resistance in primary hepatocytes, suggesting that ERα also mediates hepatic insulin sensitivity through other mechanisms." (PMID 38649684, 2024). "Similarly, both hyperinsulinemia and insulin resistance are reported to predict cardiovascular events in nondiabetic populations and a genetically predicted high insulin level is causally associated with cardiovascular morbidity." (PMID 39661465, 2024). "Furthermore, it has been observed that this intervention leads to a reduction in insulin sensitivity, as evidenced by elevated fasting blood glucose, serum insulin levels, and the homeostatic model assessment of insulin resistance index (HOMA-IR) in young wild-type mice." (PMID 38632264, 2024). "However, after controlling for BMI, VAT, and sex, myostatin/ALM was negatively associated with insulin sensitivity by Matsuda index (p = 0.03), although the association with insulin resistance by HOMA‐IR remained not significant (p = 0.07)." (PMID 39261976, 2024).
Insulin resistance (continued). "The findings indicate that the innovative beverage SPJ may have the potential to enhance insulin levels, reduce insulin resistance, regulate testosterone levels, aid in weight management, lower BMI, and decrease waist circumference among individuals diagnosed with PCOS." (PMID 39459564, 2024). "Additionally, high visceral adiposity may result in the accumulation of lipid intermediates, impair insulin signaling pathways, and induce insulin resistance, fostering an environment conducive to tumor growth, which in turn affects the survival of patients." (PMID 38690276, 2024). "This evidence is in line with the accelerator hypothesis, which indicates that increasing insulin resistance and reduced insulin sensitivity accelerate the disease process leading to type 1 diabetes only when whole glucose metabolism (secretion and peripheral action) is considered." (PMID 37914981, 2024). "Comparing MASH patients to control participants matched for body mass index and insulin resistance revealed that alterations in bile salt concentrations were associated with insulin resistance rather than liver inflammation highlighting the interaction between insulin signaling and bile salts." (PMID 38180064, 2024). "Furthermore, SO2-induced inflammation may impair insulin signaling pathways in adipose tissue, exacerbating insulin resistance and metabolic dysfunction." (PMID 39337093, 2024). "Therefore, insulin resistance can lead to inhibition of the anabolic effects of insulin resulting in muscle atrophy and sarcopenia, which may be pronounced in patients with advanced steatotic liver disease." (PMID 38474786, 2024). "Furthermore, AMPK increases insulin sensitivity and decreases insulin resistance." (PMID 39795939, 2024). "Also, we found that insulin and insulin resistance worsened in CHR during the follow-up period." (PMID 39085221, 2024). "In conditions of insulin resistance, the release of glucose from the liver (hepatic glucose output), and glucose uptake/utilization into muscle and fat (where it is stored as glycogen) are both inhibited, even in the presence of normal or elevated levels of both exogenous and endogenous insulin." (PMID 39749015, 2024). "We hypothesized that the relationship between myostatin and insulin sensitivity is independent of other risk factors for insulin resistance, such as BMI and visceral adipose tissue (VAT)." (PMID 39261976, 2024). "In addition, increased pre-hepatic insulin levels in response to insulin resistance may facilitate lipogenesis in the liver and reduced first-pass insulin clearance that may lead to hyperinsulinaemia." (PMID 38786765, 2024). "KATP channels’ relationship with insulin resistance is beginning to be explored in extra-pancreatic beta tissues like the skeletal muscle, where KATP channels are involved in insulin-dependent glucose recapture and their activation may lead to insulin resistance." (PMID 38612888, 2024). "In addition, basal insulin levels decreased, and insulin resistance (HOMA-IR) improved." (PMID 38665260, 2024). "However, over time, they may develop insulin resistance and require additional treatments such as oral medications or insulin sensitizers, similar to those used in T2DM." (PMID 39135667, 2024). "Therefore, noninvasive interventions such as exercise or dietary modifications that lower PTP1B expression could help reduce insulin resistance levels, enhance insulin function, and improve glycemic control." (PMID 38431555, 2024). "Finally, it is known that insulin can stimulate GSH synthesis; thus, an imbalance in insulin levels due to a diet rich in fructose and saturated fatty acids or due to the effects of polyphenols in insulin resistance may affect this endogenous antioxidant." (PMID 38472791, 2024).